ZNF585A (zinc finger protein 585A)
Description:
May be involved in transcriptional regulation.
Synonyms: FLJ23765; Zfp27
Tractability: PROTAC: ubiquitination databases record sites on it.
Gene: Protein-coding gene on chromosome 19 (37,106,734 to 37,172,741, reverse strand). Ensembl gene ENSG00000196967.
Subcellular location: Nucleus
Pathways (Reactome):
Gene expression (Transcription): Generic Transcription Pathway
Gene Ontology:
Molecular function: transcription cis-regulatory region binding
Biological process: regulation of transcription by RNA polymerase II; regulation of DNA-templated transcription
Cellular component: nucleus
Genetic constraint (gnomAD): Loss-of-function variants: 14 observed, 24.54 expected, observed/expected ratio (o/e) 0.57, 90% interval 0.38 to 0.89. The upper end of that interval is the gene's LOEUF score, 0.89, which puts it in group 3 of 6, group 1 being the genes least tolerant of losing a copy. Missense variants: 726 observed, 948.77 expected, observed/expected ratio (o/e) 0.77, 90% interval 0.72 to 0.81. Synonymous variants: 276 observed, 323.44 expected, observed/expected ratio (o/e) 0.85, 90% interval 0.77 to 0.94.
Homologues: Orthologues: chimpanzee ZNF585A (99% identical), macaque ZNF585A (98% identical). Paralogues in human: ZNF585B (95% identical), ZNF484 (51% identical), ZNF41 (47% identical), ZNF658 (42% identical), ZNF197 (41% identical), ZNF33B (40% identical), ZNF175 (38% identical), ZNF470 (37% identical), ZNF605 (37% identical), ZNF546 (37% identical), ZNF841 (37% identical), ZFP28 (36% identical), and 164 more.
Diseases named in the same sentence as ZNF585A in open-access papers:
ZNF585A is named in the same sentence as 1 disease in open-access papers, as found by Europe PMC text mining. Sharing a sentence is not in itself a finding about the gene and the disease. The quoted sentences say what the papers report.
tumor (1 paper, 2023). "The mutation frequencies of FAM83B, ZNF585A, DMBT1, ACACA, NOVA1, PCTH1, and ADAMTS7 were significantly higher in the high‐risk group, suggesting that these mutations may contribute to tumor development." (PMID 35616307, 2023).